IL1B (interleukin 1 beta)
Diseases named in the same sentence as IL1B in open-access papers (continued):
Sharing a sentence is not in itself a finding about the gene and the disease.
renal fibrosis (continued). "Our results indicated that the administration of MA inhibits the expression of pro-inflammatory cytokines and cell adhesion molecules such as IL-1β, TNF-α, MCP-1, and ICAM-1, suggesting that MA may ameliorate renal fibrosis by the inhibition of inflammatory response." (PMID 34588982, 2021). "We established UUO-induced renal fibrosis animal models on SD rats to identify whether a negative feedback loop involving NF-κB/TIR8 regulates in vivo IL-1β-induced EMT of tubular cells." (PMID 33945104, 2021). "It was preliminarily confirmed that PS could inhibit the release and expression of inflammatory factors such as TGF-β1, TNF-α, and IL-1β by regulating the TGF-β1/p38MAPK/NF-κB signaling pathway, to improve renal tissue injury, inflammatory factor infiltration, and renal fibrosis in GN rats." (PMID 33312224, 2020). "In wild type mice, ADR injection induced proteinuria, renal fibrosis, and increased macrophage infiltration into glomeruli (q-PCR and immnohistochemical staining of F4/80 in kidney sections) and increased production of pro-inflammatory cytokines (q-PCR for MCP-1, CD11c, TNF-α, and IL-1β)." (PMID 27196103, 2016). "We provide evidence that both factors are not able to cause changes in the expression of this lncRNA, suggesting that 3110045C21Rik may be critically involved in renal fibrosis, without being upstream regulated by TGFb of IL1b signaling." (PMID 27189340, 2016). "Indeed, the renal fibrosis indicators (i.e., FN, COL-IV, COL-1); the tubular damage indicator (i.e., KIM-1); the inflammatory indicators (i.e., TNF-α, MCP-1 and IL-1β); the oxidative stress indicators (i.e., 8-OHdG and 4-HNE) were all increased when albuminuria developed." (PMID 33811534, 2021).
acute respiratory distress syndrome (120 papers, 2005 to 2026). Progressive and life-threatening pulmonary distress in the absence of an underlying pulmonary condition, usually following major trauma or surgery. "In some SARS-CoV-2 infections, excessive NETosis is linked with the development of acute lung injury (ALI) and acute respiratory distress syndrome (ARDS) due to the creation of the NETs-IL-1β loop." (PMID 40342425, 2025). "Severe patients also exhibit high levels of IL-1β, associated with thrombi and Acute Respiratory Distress Syndrome (ARDS)." (PMID 39408907, 2024). "High levels of IL-1β, IL-6, IP-10, and TNFα have been associated with acute respiratory distress syndrome (ARDS), severe disease, and mortality following SARS-CoV-2 infection." (PMID 36865568, 2022). "Several studies showed that the NLRP3 inflammasome and IL-1β are implicated in the inflammatory response during lung injury and acute respiratory distress syndrome (ARDS)." (PMID 34209586, 2021). "Persistent elevation of cytokine concentrations in patient plasma, including TNF-α and IL-1β, is associated with poor prognosis in septic patients with acute respiratory distress syndrome (ARDS)." (PMID 31998291, 2019). "Inflammatory biomarkers, like IL-1B and IL-6, are associated with a worst outcome in patients with PH or adult respiratory distress syndrome." (PMID 30840669, 2019). "This would contribute to disease severity, since higher IL-1β levels have been associated with poor outcomes in acute respiratory distress syndrome." (PMID 29997328, 2018). "Additionally, activity of IL-1β is implicated in various conditions, including Th1 cell activation, acute respiratory distress syndrome (ARDS), fever, macrophage activation syndrome, and cytokine storms." (PMID 39518964, 2024). "Proinflammatory cytokines intercellular adhesion molecule 1 (sICAM-1) and interleukin 1β (IL-1β) have been reported to be associated with another severe condition, acute respiratory distress syndrome (ARDS), which shares several pathophysiological features with AE-IPF." (PMID 32694925, 2020). "This hyperinflammatory state is characterized by the overproduction of pro-inflammatory cytokines such as IL-6, TNF-α, and IL-1β, which can cause widespread tissue damage and contribute to the severe manifestations of COVID-19, such as acute respiratory distress syndrome (ARDS)." (PMID 40094929, 2025). "Although mechanical ventilation is a critical intervention for acute respiratory distress syndrome (ARDS), it can trigger an IL-1β-associated complication known as ventilator-induced lung injury." (PMID 40236184, 2025). "This cascade culminates in a CS characterized by excessive IL-6, IL-1β, TNF-α, and IFNs, amplifying lung inflammation and increasing susceptibility to acute respiratory distress syndrome (ARDS)​." (PMID 40330025, 2025). "In the context of infectious diseases like COVID-19, vitamin K inhibits pro-inflammatory cytokines (IL-6, IL-1β, and TNF-α) and enhances the integrity of alveolar-capillary membranes reducing the risk of acute respiratory distress syndrome (ARDS)." (PMID 40718363, 2025). "Excessive NET generation is associated with the development of tissue damage during acute lung injury and acute respiratory distress syndrome, owing to the formation of inflammatory cascades in a vicious loop with interleukin (IL)-1β." (PMID 38612515, 2024). "IL1B (interleukin 1 beta) was considered an essential pro-inflammatory cytokine related to the origination and development of acute respiratory distress syndrome (ARDS)." (PMID 35227280, 2022). "In acute respiratory distress syndrome, NETs aggravate alveolar macrophage pyroptosis, and ASC foci, caspase-1, IL-1β, IL-6, and TNF-α are significantly associated with elevated NETs." (PMID 36430491, 2022). "The proportion of LOX-1- or CD123-expressing ImNs is positively correlated with clinical severity, cytokine storm (IL-1β, IL-6, IL-8, TNFα), acute respiratory distress syndrome (ARDS), and thrombosis." (PMID 34616409, 2021).
acute respiratory distress syndrome (continued). "In summary, LPS activated immune cytokines (IL-1B, IL6), induced the expression of HP, and further induced acute inflammatory response, and then caused the Acute respiratory distress syndrome." (PMID 34519633, 2021). "Targeting inflammasome activation to modulate interleukin (IL)-1β is a promising treatment strategy against acute respiratory distress syndrome and ventilator-induced lung injury (VILI)." (PMID 32117318, 2020). "Severe cases result in acute respiratory distress syndrome (ARDS) with systemic inflammation in which lung injury is associated with release of inflammatory cytokines IL-6 and IL-1β." (PMID 32655582, 2020). "The GSK3B inhibitor reduces the production of IL-6, TNFα, IL-17, and IL-1β in the BALF of mice with lipopolysaccharide-induced acute respiratory distress syndrome, thus relieving the lung injury." (PMID 31466385, 2019). "Recent studies have found that IL-1β is the major cytokine inducing lung inflammation in acute respiratory distress syndrome, which involves a decrease in blood oxygen that is sufficient to cause hypoxic damage." (PMID 29254155, 2017). "Pro-inflammatory interleukins like IL-1β, IL-6, IL-2, IL-17 and IL-18 are critically involved in cytokine storm, hyperinflammation, and acute respiratory distress syndrome, whereas anti-inflammatory cytokines like IL-10 contribute to immune regulation and resolution of inflammation." (PMID 41683812, 2026). "The cytokine storm phenomenon is an increase in pro-inflammatory cytokine levels in the serum, such as IL-2, IL-6 and IL-1β, IL-17, IL-8, G-CSF, GM-CSF, IP10, MCP1, MIP1α (also known as CCL3), and TNF, and causes acute respiratory distress syndrome (ARDS) in severe COVID-19 cases." (PMID 37626992, 2023). "A cytokine storm, characterized by excessive production of pro-inflammatory cytokines—particularly TNF-α, IL-6, and IL-1β—can trigger multiorgan damage and acute respiratory distress syndrome (ARDS)." (PMID 40807350, 2025). "The excessive production of IL-6, TNF, and IL-1β in glycolysis-driven immune cells results in widespread tissue damage, endothelial dysfunction, and acute respiratory distress syndrome (ARDS)." (PMID 40453076, 2025). "It has been involved in modifying the pathogenesis of acute respiratory distress syndrome (ARDS), regulating the production of IL1-β, and IL-1 receptor antagonists and the subsequent pulmonary access of neutrophils." (PMID 34407143, 2021). "IL-1β has been identified as an important cytokine in patients with the acute respiratory distress syndrome (ARDS), a neutrophil mediated disease." (PMID 16759367, 2006). "However, excessive TNF-α synergizes with IL-6 and IL-1β, leading to increased vascular permeability, pulmonary edema, and multi-organ damage, especially in acute respiratory distress syndrome (ARDS)." (PMID 41592028, 2026). "The binding of SARS-CoV-2’s spike protein to ACE2 leads to dysregulation, contributing to acute respiratory distress syndrome (ARDS), hypertension, and the overproduction of cytokines such as IL-1β, IL-17A, and IL-18." (PMID 40003732, 2025). "It has been confirmed to alleviate lung injury of acute respiratory distress syndrome by down-regulating the mRNA expression of inflammatory factors such as TNF-α, IL-6, and IL-1β, as well as by reducing neutrophil infiltration." (PMID 37547679, 2023). "As an example, BALF-EVs increase interleukins IL-1β and IL-6, Tumor Necrosis Factor α (TNFα), and CC motif chemokine Ligand 2 (CCL2) in sarcoidosis disease and acute respiratory distress syndrome (ARDS)." (PMID 36768664, 2023). "A suppression of NF-ĸB-dependent gene expression, including IL-1β, TNF-α, and VCAM-1, was also observed with olaparib in a mouse model of acute respiratory distress syndrome." (PMID 35740913, 2022).
acute respiratory distress syndrome (continued). "Metformin, as the first-line medication for the treatment of diabetes, inhibited NLRP3 inflammasome activation and IL-1β production in cultured and alveolar macrophages, thus attenuating LPS and SARS-CoV-2-induced acute respiratory distress syndrome (ARDS)." (PMID 35847986, 2022). "Exuberant host responses, i.e., a cytokine storm with increase of macrophage-related cytokines, such as TNFα, IL-1β, and IL-6 can lead to life-threatening complications, such as acute respiratory distress syndrome (ARDS), which develops in approximately 20% of the patients." (PMID 32916949, 2020). "IL-1β is one of the major inflammatory cytokines in ALI/acute respiratory distress syndrome (ARDS)." (PMID 28346367, 2017). "IL-1β is one of the most biologically active cytokines in edema fluid and bronchoalveolar lavage (BAL) fluid from patients at an early stage of acute respiratory distress syndrome (ARDS)." (PMID 22558159, 2012). "Additionally, rosmarinic acid alleviated LPS-induced acute respiratory distress syndrome in mice, wherein it lowered the expression of TNF-α and IL-1β in the lung at protein level." (PMID 39129025, 2024). "Excessive IL-6, IL-1β, and TNFα levels along with increased recruitment of immune cells in the airways contribute to epithelial damage and acute lung injury, driving the development of acute respiratory distress syndrome (ARDS), leading to severe vascular leakage and pulmonary edema." (PMID 35846766, 2022). "Massive systemic release of pro-inflammatory mediators such as interleukin (IL)-1β, IL-2, IL-6, IL-7, IL-10, tumor necrosis factor-α (TNFα), granulocyte colony-stimulating factor (G-CSF), etc., also known as cytokine storm, contributes to the acute respiratory distress syndrome (ARDS)." (PMID 35888733, 2022). "Indeed, increased TNF-α, IL-1β, and IL-6 levels were detected in the BALF of patients with acute respiratory distress syndrome." (PMID 34745417, 2021). "Acute respiratory distress syndrome (ARDS) is the leading cause of death in COVID-19 patients, and DPP4 inhibitors may be a new treatment approach because they can decrease the production of inflammatory factors such as IL-1β, TNF-α, and IL-6." (PMID 34955820, 2021). "This process triggers the excessive production of proinflammatory cytokines, including IL-6, IL-1β, and TNF-α, contributing to acute respiratory distress syndrome (ARDS), which is characterized by pulmonary edema, hypoxemia, and respiratory failure." (PMID 41521316, 2026). "Furthermore, in a model of LPS-induced Acute respiratory distress syndrome (ARDS), treatment with pyridostigmine reduced the number of macrophages and lymphocytes in bronchoalveolar lavage fluid and suppressed levels of TNFα, IL-1β, IL-6, and IFN-γ." (PMID 34948222, 2021). "NLRP3 inflammasome overactivation produces excessive IL-1β and downstream cytokines such as IL-6 and TNF-α, are also observed in acute respiratory distress syndrome (ARDS), ventilator induced lung injury (VILI), and disseminated intravascular coagulation (DIC)." (PMID 34150848, 2021). "In COVID-19 assessed by scRNA-seq, SARS-CoV-2 infection induced IL-1β and TNF-α production may promote mucin secretion from club cells, likely contributing to acute respiratory distress syndrome (ARDS)." (PMID 33106757, 2020). "Acute lung injury/acute respiratory distress syndrome (ALI/ARDS) is also associated with an overwhelming inflammatory response: proinflammatory cytokines IL-1β and IL-18 levels are high in bronchoalveolar lavage fluid from patients with ALI/ARDS and correlate with mortality." (PMID 28740332, 2017). "This exaggerated response leads to the production of a number of pro-inflammatory cytokines including IL-1β, IL-2, IL-6, IFN-γ, and TNF-α, which can lead to endothelial cell injury, acute lung injury (ALI), acute respiratory distress syndrome (ARDS), and vascular collapse (shock)." (PMID 24141285, 2013).
acute respiratory distress syndrome (continued). "Similarly, in a mouse model of acute respiratory distress syndrome (ARDS), treatment with THC led to a 100% survival rate, a reduction in the infiltration of immune cells into the lungs, and a reduction in the proinflammatory cytokines IFN-γ, IL-1β, IL-2, IL-6, and TNF-α." (PMID 38202234, 2023).
liver inflammation (119 papers, 2008 to 2026). "TNF-α causes damage to hepatocytes and induces the production of IL-1β and IL-6, thereby causing hepatocyte apoptosis and liver inflammation." (PMID 38999886, 2024). "The NLRC4 inflammasome has been shown to be crucial in bacterial infections in the liver, and NLRC4-mediated IL-1β release has been linked to liver inflammation." (PMID 36969233, 2023). "Liver immune cells and the proinflammatory cytokines they produce, including Interleukin 6 (IL-6), Tumor Necrosis Factor Alpha (TNFα) and Interleukin 1 beta (IL-1β), have all been implicated in driving behavioral changes in the setting of liver inflammation." (PMID 37521690, 2023). "In brief, these results demonstrated that caspase-1 was required for IL-1β production in ConA-induced hepatitis and caspase-1 deficiency prevented NLRP3 inflammasome activation and pyroptosis, thus ameliorating liver inflammation and injury." (PMID 29692782, 2018). "The initial analysis on the detection of inflammatory factors in the liver such as TNF-ɑ, IL-1β, IL-6, and iNOS revealed the association between hepatitis and monocyte-macrophage cells." (PMID 29599918, 2018). "Collectively, these results indicated that NLRP3 played a pathogenic role in the pathogenesis of ConA-induced hepatitis through eliciting IL-1β production and pyroptosis." (PMID 29692782, 2018). "Taken together, we propose a mechanism of aging-specific vulnerability against endotoxin-induced liver inflammation and suggest a pathogenic role of the inflammasome/IL-1β pathway on liver lipid accumulation." (PMID 25847140, 2015). "Based on these results, we propose a mechanism of aging-specific vulnerability against endotoxin-induced liver inflammation and suggest a pathogenic role of the inflammasome/IL-1β pathway in liver lipid accumulation." (PMID 25847140, 2015). "It is a common perspective that the progress of hepatitis is associated with a series of proinflammatory cytokines such as IL-2, IL-6, IL-1β and TNF-α." (PMID 24498418, 2014). "TNF-α, IL1β and IL-6 are the cytokines most commonly associated with liver inflammation, while CD64 and CD68 are markers of Kupffer cell activation." (PMID 23755290, 2013). "Hepatitis-related inflammatory cytokines, such as interleukin-6 (IL-6) and interleukin-1β (IL-1β), have been identified as core promoters of susceptibility to an HBV infection, persistence of an HBV infection, and the initiation, promotion, and progression of the development of HBV-related HCC." (PMID 34451963, 2021). "Studies on oleanolic acid (a key constituent of akebia) have demonstrated its capacity to suppress the production of pro-inflammatory cytokines, including IL-6 and IL-1β, by inhibiting the NF-κB signaling pathway in murine models of liver inflammation." (PMID 41295685, 2025). "NLRP3 inflammasome activation induces the secretion of cytokines such as IL1β, which plays a role in inducing liver inflammation and fibrosis." (PMID 40089787, 2025). "This phenotype is closely associated with abnormal activation of the NLRP3 inflammasome, a key driver of hepatitis that initiates inflammatory cascades through Caspase-1-mediated maturation of IL-1β and IL-18." (PMID 40868283, 2025). "It appears to either directly or indirectly suppress the expression of pro-inflammatory cytokines such as TNF, IL6, and IL1B, thus alleviating liver inflammation." (PMID 38755697, 2024). "Patients with AIH were found to have very high levels of IL-1β that correlated with the aggravation of hepatitis, probably due to the key role of IL-1β as a mediator of inflammation between the macrophages and lymphocytes." (PMID 38674122, 2024). "Upon binding to its receptor on the KCs, IL-1β acts as a mediator of liver inflammation, since it sustains the activation of resident macrophages and contributes to hepatitis and fibrosis." (PMID 38674122, 2024).